EFCAB3 (EF-hand calcium binding domain 3)
Synonyms: FLJ25818
Tractability: No criterion of Open Targets' tractability assessment is met for any kind of drug.
Gene: Protein-coding gene on chromosome 17 (62,343,941 to 62,416,480, forward strand). Ensembl gene ENSG00000172421.
Gene Ontology:
Molecular function: calcium ion binding
Genetic constraint (gnomAD): Loss-of-function variants: 39 observed, 46.24 expected, observed/expected ratio (o/e) 0.84, 90% interval 0.65 to 1.1. The upper end of that interval is the gene's LOEUF score, 1.1, which puts it in group 4 of 6, group 1 being the genes least tolerant of losing a copy. Missense variants: 413 observed, 513.95 expected, observed/expected ratio (o/e) 0.8, 90% interval 0.74 to 0.87. Synonymous variants: 169 observed, 178.23 expected, observed/expected ratio (o/e) 0.95, 90% interval 0.84 to 1.08.
Homologues: Orthologues: chimpanzee EFCAB3 (99% identical), macaque EFCAB3 (96% identical), dog EFCAB3 (82% identical), rabbit EFCAB3 (81% identical), pig EFCAB3 (75% identical), guinea pig EFCAB3 (74% identical), Caenorhabditis elegans cal-1 (9% identical), Caenorhabditis elegans E02A10.3 (9% identical), Caenorhabditis elegans cal-3 (9% identical), Caenorhabditis elegans tnc-2 (9% identical), Caenorhabditis elegans B0563.7 (8% identical), Caenorhabditis elegans F35C12.3 (8% identical), and 6 more. Paralogues in human: CABP2 (11% identical), CABP4 (11% identical), CALM1 (11% identical), CALM2 (11% identical), CALM3 (11% identical), CALML3 (11% identical), CETN2 (11% identical), CETN1 (11% identical), EFCAB7 (11% identical), CETN3 (10% identical), CABP1 (10% identical), CABP5 (10% identical), and 8 more.
Diseases named in the same sentence as EFCAB3 in open-access papers:
EFCAB3 is named in the same sentence as 2 diseases in open-access papers, as found by Europe PMC text mining. Sharing a sentence is not in itself a finding about the gene and the disease. The quoted sentences say what the papers report.
breast tumors (1 paper, 2020). "Located within the inactive TADs, five of the six aforementioned non-ATC loci (except EFCAB3) were highly methylated at shore regions of CpG island promoters (i.e., TBX2, TBX4, MRC2, and MARCH10) and non-CpG island promoter (i.e., NACA2) in 77 breast tumors compared to 10 normal controls (ref. #)." (PMID 32408897, 2020).
cancer (2 papers, 2014). A tumor composed of atypical neoplastic, often pleomorphic cells that invade other tissues. "While three of the chimeras (ACTB->POTEM, ACTB->POTEE and SP100->HMGB1) have been found in normal population, three of the chimeras (C2orf27A->NBEA, HILPDA->EFCAB3, FARSB->TRIM61) were previously identified only in cancer samples." (PMID 25133550, 2014). "Moreover, we implicate several of these gene hits not only in ccRCC for the first time (BHLHB3, CAMK1, CDH13, ENPP3, KCNJ2, KSR1, PLOD2, and TCF8), but also in a cancer model for the first time (CEP290, EFCAB3, PGBD5, RAPGEF5, SSPN, and TOX2)." (PMID 24979721, 2014).